RNU6-1296P (RNA, U6 small nuclear 1296, pseudogene)
Gene: Small nuclear RNA gene on chromosome 5 (51,167,541 to 51,167,647, reverse strand). Ensembl gene ENSG00000206606.
Homologues: Orthologues: chimpanzee U6 (96% identical), macaque U6 (93% identical), rabbit U6 (67% identical). Paralogues in human: RNU6-38P (85% identical), RNU6-44P (85% identical), RNU6-10P (84% identical), RNU6-1145P (84% identical), RNU6-41P (84% identical), RNU6-639P (84% identical), RNU6-1107P (83% identical), RNU6-17P (83% identical), RNU6-18P (83% identical), RNU6-20P (83% identical), RNU6-25P (83% identical), RNU6-29P (83% identical), and 1286 more.